TLR7 (toll like receptor 7)
Diseases named in the same sentence as TLR7 in open-access papers (continued):
Sharing a sentence is not in itself a finding about the gene and the disease.
ZIKV infection (11 papers, 2017 to 2024). "Stimulation of TLR3 (using poly I:C) or TLR7 (using Imiquimod) prior to ZIKV infection suppressed viral replication in a dose-dependent manner." (PMID 32941515, 2020). "The toll-like receptor 7 (TLR7), a specialized sensor that recognizes RNA viruses and triggers the antiviral response, has been implicated in the regulation of ZIKV infection." (PMID 31212905, 2019). "It was shown that the type 1 interferon (IFN) responses, which can be achieved through TLR7/9 activation, can attenuate the ZIKV infection and consequent neurological alterations." (PMID 31212905, 2019). "The stronger inhibitory response after ZIKV infection on a selected group of genes when the TLR7/8 signaling pathway was blocked in both cell lines demonstrates its role in the intracellular innate immune response." (PMID 30453684, 2018). "Thus, a potential explanation for the inhibition of VDR and CAMP mRNA expression by ZIKV infection could involve the expression of innate immune receptors, such as TLR7 and TLR8, that recognize intracellular viral RNA." (PMID 38839691, 2024). "As TLR7 is mainly activated by single stranded RNA, we hypothesize that this increase in the TLR7 expression could lead to an enhanced activation of anti-viral cell signaling pathways, limiting ZIKV infection." (PMID 31212905, 2019). "ZIKV infection has been shown to activate intracellular TLRs such as TLR3 and TLR7/8 and to promote a strong pro-inflammatory and antiviral response." (PMID 38839691, 2024). "Our data from our poly(I:C) pre-stimulation studies support previous studies that demonstrated the protection of host cells from ZIKV infection following the activation of TLR3, RIG-I and TLR7/8 pathways." (PMID 35053142, 2022). "Specifically, we studied the role of TLR7, TLR8, and STAT2 during ZIKV infection, since they are key molecules in the cellular antiviral and IFN-mediated responses." (PMID 30453684, 2018). "Although ZIKV infection downregulates TLR7 and TLR8 mRNA expression in human monocytes, we did not observe any effect of VitD3 treatment on TLR7 and TLR8 mRNA expression in either ZIKV-Mon or ZIKV-VitD3-Mon when compared to VitD3-Mon." (PMID 38839691, 2024). "To gain preliminary insight into whether stimulation of IFN response prior to ZIKV infection can decrease or block viral replication, we pre-treated fcMSCs from one of the donors for 1 h with TLR3 or TLR7 agonists poly I:C or imiquimod, respectively." (PMID 32941515, 2020). "ZIKV infection of engineered or wild-type (WT) cells revealed that the KD of RIG-I, but not TLR7 and TLR8, conspicuously attenuated the ZIKV-induced pyroptotic cell death and GSDME cleavage, suggesting that RIG-I may play a major role in ZIKV-induced pyroptosis." (PMID 35972780, 2022).
anemia (10 papers, 2014 to 2025). A reduction in the number of red blood cells, the amount of hemoglobin, and/or the volume of packed red blood cells. "Though a result of multiple causes, anemia can also be driven by chronic TLR-7 and TLR-9 signaling, initiating the differentiation of inflammatory hemophagocytes." (PMID 37508529, 2023). "The anemia observed in NASA patients almost certainly is due to severe chronic systemic autoinflammation rather than immune-mediated mechanisms (as occurs in patients with TLR8 mutations causing TLR7-mediated autoinflammation)." (PMID 37744344, 2023). "It is reported that functional activation of TLR7 might lead to the loss of body weight and a decrease in platelet counts, and chronic TLR7 signaling drives anemia through the differentiation of specialized hemophagocytes." (PMID 36499455, 2022). "Anemia, autoimmune hemolytic, autoinflammation, X-linked TRAF6-mediated NF-kB, and MAP kinase up-regulation in response to TLR7/8 or 9 activations is related mechanisms." (PMID 36004808, 2022). "More profound changes were seen in their blood counts, as TLR7-stimulated mice had statistically and clinically significant anemia as well as a leukocytosis." (PMID 31998321, 2019). "A higher count of CD3+, CD4+, and CD19+ cells coexpressing TLR7 was found in patients with anemia compared to subjects with hemoglobin above 12 g/dL." (PMID 24692849, 2014). "The observed higher percentage of CD3+, CD4+, and CD19+ cells with TLR7 among subjects with anemia may reflect the presence of chronic inflammation and increased proinflammatory cytokines." (PMID 24692849, 2014). "Among patients with anaemia, there was a higher percentage of TLR7-positive CD3+ (4.19% ± 5.45), CD4+ (4.19% ± 5.45), and CD19+ cells (5.87% ± 8.71), compared to patients with haemoglobin concentration >12 g/dL (0.55% ± 1.08, P < 0.05; 0.55% ± 1.08, P < 0.03; 0.85% ± 2.24, P < 0.02, resp)." (PMID 24692849, 2014).
lymphoma (10 papers, 2012 to 2023). A malignant (clonal) proliferation of B- lymphocytes or T- lymphocytes which involves the lymph nodes, bone marrow and/or extranodal sites. "Activating mutations in MyD88 have been described in human lymphomas, suggesting that constitutive human TLR7 or TLR8 signaling in our mice could be driving proliferation." (PMID 25229618, 2014). "In syngeneic human CD20- (hCD20-) expressing models of lymphoma, systemic administration of a TLR7 agonist (R848) reportedly augmented responses upon combinatorial administration with obinutuzumab, thus preventing tumor recurrence." (PMID 32377528, 2020). "Here we demonstrate, in syngeneic human CD20 (hCD20)-expressing models of lymphoma, that systemic administration of a TLR7 agonist (R848) increases responses when administered in combination with obinutuzumab and protects against disease recurrence." (PMID 27890931, 2017). "We demonstrate that addition of systemically administered TLR7 agonist R848 to obinutuzumab therapy can significantly enhance long-term survival in syngeneic models of lymphoma." (PMID 27890931, 2017). "In this study, we focused on establishing a therapeutic schedule with the proper dose for the treatment of lymphoma using a TLR7 agonist synthesised in our lab combined with chemotherapeutic drugs in a murine T cell lymphoma model." (PMID 25887995, 2015). "Immune stimulation through TLR7 activation in combination with obinutuzumab is hypothesized to further enhance lymphoma clearance and the generation of long-term antitumor immune responses." (PMID 32377528, 2020). "To establish whether systemic administration of a TLR7 agonist could improve obinutuzumab efficacy we developed a syngeneic model of lymphoma in immune-competent mice." (PMID 27890931, 2017). "We hypothesized that immune stimulation through Toll-like receptor 7 (TLR7) agonism in combination with obinutuzumab would further enhance lymphoma clearance and the generation of long-term antitumor immune responses." (PMID 27890931, 2017). "In this study, as most of the murine lymphoma cells expressed endogenous TLR7, we sought to investigate whether SZU-101 had a direct effect on the tumour cells." (PMID 25887995, 2015). "In human lymphoma, the expression of TLR7 has been demonstrated in several studies." (PMID 25887995, 2015). "However, using models of lymphoma we have recently published that combination therapy with a systemic TLR7 agonist and local IR leads to the induction of a durable CD8+ T-cell response that mediates antitumor activity and increases survival." (PMID 24390981, 2014). "Therefore, we chose to use R848, which binds selectively to mouse TLR7, to develop a syngeneic murine lymphoma model to investigate whether TLR7 agonism can enhance the efficacy of anti-CD20 antibodies by priming of T-cell responses." (PMID 27890931, 2017).
Psoriasiform dermatitis (10 papers, 2016 to 2026). A skin abnormality characterized by redness and irritation, with thick, red skin that displays flaky, silver-white patches (scales). "For example, WD feeding exacerbated susceptibility to the TLR7 agonist imiquimod, leading to the development of psoriasiform dermatitis." (PMID 38464106, 2024). "Therefore, we hypothesized that studying slc15a4 deficiency in the IMQ psoriasiform dermatitis model may clarify the role of the TLR7-pDC-IFN-I pathway of immune pathology." (PMID 30262916, 2018). "Unfortunately, the lack of species cross-reactivity of A-552 to mouse IL-36α or IL-36γ precluded assessing the effects of this inhibitor in preclinical mouse models of psoriasiform dermatitis induced by injection of IL-23 or the TLR7 agonist IMQ." (PMID 31235749, 2019). "Here we extend our analysis of slc15a4 to examine its role in psoriasiform dermatitis mediated by the canonical TLR7 agonist imiquimod as compared to intradermal IL23 injection." (PMID 30262916, 2018). "Concomitantly, pDCs and cDCs cooperatively activate autoreactive naive T cells for the differentiation of Teff cells to initiate psoriasiform dermatitis under TLR7-mediated inflammatory conditions." (PMID 27075414, 2016). "The imiquimod (IMQ)-induced psoriasiform dermatitis acts via Toll-like receptor 7 (TLR7) stimulation with daily application of Aldara® cream, which contains IMQ." (PMID 27317338, 2016). "Analysis of gene-modified mice suggests that the initiation of IMQ-induced psoriasiform dermatitis involves the TLR7- and IFNAR1-mediated signaling cascades, whereas the activation of CD4+ Teff cells through costimulation by APCs contributes to the disease progression." (PMID 27075414, 2016).
chronic lymphocytic leukemia (9 papers, 2016 to 2026). "On the other hand, an opposite role has been described for TLR7 agonists in cell chronic lymphocytic leukemia cells where TLR7 stimulation acts as a pro-survival factor." (PMID 34884547, 2021). "In multiple myeloma and chronic lymphocytic leukemia (CLL), TLR7 activation promotes tumor cell survival, proliferation, and the secretion of pro-inflammatory cytokines." (PMID 40495154, 2025). "In this setting, chronic lymphocytic leukemia- (CLL-) derived exosomes transfer noncoding Y RNA hY4 to monocytes, inducing PD-L1 expression via toll-like receptor 7 (TLR-7) signaling." (PMID 33628854, 2021). "Indeed, an increased expression of both CD86 and CD80 in response to TLR9 stimulation was shown in chronic lymphocytic leukemia, but not in response to TLR7 stimulations." (PMID 29805758, 2018).
Cirrhosis (9 papers, 2014 to 2023). A chronic disorder of the liver in which liver tissue becomes scarred and is partially replaced by regenerative nodules and fibrotic tissue resulting in loss of liver function. "While TLR7 expression is downregulated in tumor lesions of HBV- and HCV-associated HCC as compared to non-viral etiologies, another study finds TLR7 overexpressed in HCC lesions as compared to tissues from cirrhosis or viral hepatitis." (PMID 33613561, 2020). "TLR7 downregulation in late stage of fibrosis is likely a consequent of immune evasion strategy used by the virus, which might account for its success in establishing chronic infection that ends in cirrhosis." (PMID 27135246, 2016). "We have previously shown that neutrophils isolated from patients with cirrhosis and exposed to CL097 or R848 (which are agonists for endosomal TLR7/8) had an increased superoxide production in response to fMLP." (PMID 33613548, 2020). "To expand these results, we performed comparative analysis of TLR7, LC3A/B, and IGF-1 in mice under normal, NAFLD, and cirrhosis conditions." (PMID 27279075, 2016). "To investigate hepatic IGF-1 content in all stages of chronic liver disease, we performed comparative analysis of protein expression of TLR7, LC3A/B, and IGF-1 in livers from mice under normal, NAFLD, and cirrhosis conditions." (PMID 27279075, 2016). "In the present study, TLR7 expression was higher in human HCC cases than that with viral hepatitis, cirrhosis and Normal controls." (PMID 27588480, 2016). "High expression levels of TLR7 and TLR9 have been observed in liver tissue microarrays of patients with cirrhosis, viral hepatitis, and hepatocellular cancer." (PMID 27456065, 2016). "The effects of TLR7/8 agonists on these adaptive immunity cells in the context of cirrhosis are not known." (PMID 31134093, 2019). "TLR7 and LC3A/B expression were reduced in both NAFLD and cirrhosis." (PMID 27279075, 2016). "Most of these alterations are reversible ex vivo with TLR7/8 agonists (CL097, R848), raising the possibility that these agonists might be used in the future to restore neutrophil antibacterial functions in patients with cirrhosis." (PMID 31134093, 2019). "However, the role of TLR7 and the efficacy of its agonists in NAFLD, which ranges from simple steatosis that can progress to NASH and then to fibrosis or cirrhosis, is unknown." (PMID 27279075, 2016). "Most of adjacent non-cancerous tissues had cirrhosis background, so the expression of TLR7 may differ in normal livers and non-cancerous liver tissues." (PMID 27588480, 2016).
Hepatitis (9 papers, 2017 to 2025). Inflammation of the liver. "In the present case report, we identified a male child with the tlr-7 gene Gln11Leu single nucleotide polymorphism (rs 179008) with hepatitis and positive serological SARS-CoV-2 test." (PMID 34482844, 2021). "TLR7 agonists have been used therapeutically to treat herpes simplex virus and hepatitis C, due to their ability to provoke an IFN-mediated adaptive immune response to the virus." (PMID 34991643, 2022). "In this study, the role of TLR7 in S. japonicum infection-induced hepatitis was investigated in both normal and TLR7 knockout (KO) C57BL/6 mice." (PMID 34692568, 2021). "Altogether, this study indicated that TLR7 could delay the progression of S. japonicum infection-induced hepatitis mainly through macrophages." (PMID 34692568, 2021). "Altogether, this study indicated that TLR7 could delay the progression of S. japonicum infection-induced hepatitis by facilitating the formation of granulomas mainly through hepatic macrophages." (PMID 34692568, 2021). "Liver inflammation, assessed by ALT levels, correlated with platelet- and leukocyte-LGP2, in addition to leukocyte-TLR3, -TLR6, -TLR7, and -RIG-I." (PMID 40825056, 2025). "The study on role of TLR7 in HBV infection has been shown in HepG2.2.15 cell line, harboring multiple copies of HBV genome, since the supernatant from the cell culture can infect chimpanzees intravenously, showing typical symptoms of human hepatitis, highlighting the efficiency of the model." (PMID 28088184, 2017).
hepatitis B (9 papers, 2014 to 2023). "Additionally, several TLR7 agonists have been shown to improve immunity of hepatitis B-infected hosts and are implicated as potential HBV vaccine adjuvants." (PMID 33679711, 2020). "The activation of TLR-7 has been suggested to modulate hepatitis B, herpes simplex and human papillomavirus infections." (PMID 37508529, 2023). "The TLR7 agonist imiquimod and the TLR7/8 agonist resiquimod have also been combined with protein subunit vaccines for hepatitis B in separate phase II and phase III trials." (PMID 34571909, 2021). "TLR7 compounds are under investigation as vaccine adjuvant strategies for hepatitis B as well, including Vesatolimod (GS-9620; NCT02166047) and R07020531 (NCT02956850)." (PMID 33679711, 2020). "This review focuses on anti-viral strategies that involve targeting TLR7 that may lead to development of protective immunity and eradication of hepatitis B." (PMID 24884741, 2014). "A CpG-based adjuvant is used in an FDA-approved hepatitis B vaccine (Heplisav-B), and the ssRNA component in the influenza A WIV vaccine is critical for its intrinsic adjuvant activity via TLR7 activation." (PMID 36757205, 2023). "The TLR7 agonists tested to date in phase I trials include GS-9620, RO7020531 and TQ-A3334 were all shown to be safe and well tolerated in hepatitis B patients and healthy volunteers." (PMID 34571909, 2021). "Its therapeutic effect, however, cannot be hepatocyte- or liver-specific due to TLR-7 expression profiles, and further clinical trials are needed to judge the suitability of TLR-7 agonists as hepatitis B therapeutics." (PMID 28117695, 2017). "In the case of Hepatitis B vaccines, they have been combined with TLR4, TLR7, TLR8 TLR9 agonists." (PMID 34571909, 2021).
lymphopenia (9 papers, 2009 to 2025). Reduction in the number of lymphocytes. "We previously demonstrated that triggering of TLR7 causes immune incompetence in mice by induction of lymphopenia." (PMID 19290047, 2009). "Thus we reasoned that TLR7 induced lymphopenia might increase susceptibility to pneumococcal superinfection." (PMID 19290047, 2009). "Patients who received PF4878691, a TLR7 agonist that was developed for treating hepatitis C virus, showed flu-like symptoms, lymphopenia and hypotension." (PMID 35369443, 2022). "We have shown that triggering of TLR7 by the specific ligand R-848 rapidly induces lymphopenia in mice lasting 36–48 hours." (PMID 19290047, 2009). "The loss of TLR7 in the B cell is sufficient to suppress several of the hallmark cellular manifestations of SLE in Tlr9–/– MRL/lpr mice, including T cell activation and B cell lymphopenia." (PMID 37606042, 2023). "In addition, we have previously shown that TLR7-triggering with the imidazoquinoline R-848 induces lymphopenia and leads to transient immune-incompetence in the host." (PMID 19290047, 2009). "IAV is recognized by TLR7 and infections can lead to lymphopenia." (PMID 19290047, 2009). "Although TLR7-mediated lymphopenia did not affect the overall survival of S. pneumoniae-infected mice it was still possible that lymphopenia showed more subtle effects on bacterial spread." (PMID 19290047, 2009). "While TLR7-triggering induces lymphopenia it does not equally well deplete PMN from the blood." (PMID 19290047, 2009). "However, lymphopenia forced by TLR7-triggering or antibody-mediated neutropenia did not increase SP-susceptibility or compromise the ability to control SP growth." (PMID 19290047, 2009).
non-small cell lung carcinoma (9 papers, 2021 to 2025). A group of at least three distinct histological types of lung cancer, including non-small cell squamous cell carcinoma, adenocarcinoma, and large cell carcinoma. "Studies have shown that TLR7 can be used as a reliable marker of poor prognosis, which reveals the high expression of TLR7 in patients with non-small cell lung cancer, which is related to the inflammatory process of TLR7 signaling." (PMID 36591509, 2022). "We found that TLR7 exerts antitumor functions in non-small cell lung cancer by inducing the production of specific molecules with inhibitory properties against new blood vessel formation." (PMID 33578955, 2021). "Indeed, tumour cell-intrinsic expression of TLR7 and TLR8 promotes their growth and survival in vitro and is associated with poor clinical outcome in non-small cell lung carcinomas (NSCLC)." (PMID 40336011, 2025). "For example, higher levels of TLR7/8 and 9 were found in non-small cell lung carcinoma (NSCLC) than in normal lung tissue." (PMID 35884895, 2022). "TLR7 and TLR8 activation in non-small cell lung cancer induced survival of cancer cell lines and increased cancer cell chemoresistance." (PMID 38709790, 2024). "TLR4, TLR5, TLR7, and TLR8 were more highly expressed in non-small cell lung cancer (NSCLC)." (PMID 41471188, 2025).